DCDC1 (doublecortin domain containing 1)
Description:
Microtubule-binding protein which plays an important role in mediating dynein-dependent transport of RAB8A-positive vesicles to the midbody during cytokinesis.
Synonyms: DCDC5; FLJ46154
Tractability: PROTAC: ubiquitination databases record sites on it; its protein half-life has been measured.
Gene: Protein-coding gene on chromosome 11 (30,830,369 to 31,369,810, reverse strand). Ensembl gene ENSG00000170959.
Subcellular location: Midbody, Midbody ring; Midbody; Cytoplasm, cytoskeleton, spindle
Gene Ontology:
Molecular function: microtubule binding; protein binding
Biological process: regulation of mitotic cytokinesis; intracellular signal transduction
Cellular component: Flemming body; midbody; mitotic spindle; spindle
Genetic constraint (gnomAD): Loss-of-function variants: 127 observed, 134.6 expected, observed/expected ratio (o/e) 0.94, 90% interval 0.82 to 1.09. The upper end of that interval is the gene's LOEUF score, 1.09, which puts it in group 4 of 6, group 1 being the genes least tolerant of losing a copy. Missense variants: 1,496 observed, 1,455 expected, observed/expected ratio (o/e) 1.03, 90% interval 0.99 to 1.07. Synonymous variants: 510 observed, 505.03 expected, observed/expected ratio (o/e) 1.01, 90% interval 0.94 to 1.09.
Homologues: Orthologues: chimpanzee DCDC1 (99% identical), dog DCDC1 (84% identical), pig DCDC1 (83% identical), rabbit DCDC1 (80% identical).
Diseases named in the same sentence as DCDC1 in open-access papers:
DCDC1 is named in the same sentence as 16 diseases in open-access papers, as found by Europe PMC text mining. Sharing a sentence is not in itself a finding about the gene and the disease. The quoted sentences say what the papers report.
aniridia (5 papers, 2011 to 2023). Aniridia is a congenital ocular malformation characterized by the complete or partial absence of the iris. "In this study, the novel 517 kb heterozygous deletion (chr11:31,139,019–31,655,997) downstream of PAX6 containing four annotated genes, DCDC1, DNAJC24, IMMP1L, and ELP4, is likely to be the cause of the familial aniridia in this Chinese family." (PMID 37752489, 2023). "Taken together, a 517 kb heterozygous deletion containing four annotated genes, DCDC1, DNAJC24, IMMP1L, and ELP4, was identified in this Chinese family with congenital aniridia, suggesting that transcription-regulating elements in the deleted region are required for the expression of PAX6." (PMID 37752489, 2023). "Recently a ~406 kb heterozygous genomic deletion containing four annotated genes (DCDC1, DNAJC24, IMMP1L, and ELP4) was found in patients with aniridia; apparently the gene contents in this deletion are the same as the 566 kb heterozygous deletion in the family we report here." (PMID 21321669, 2011).
esophageal cancer (3 papers, 2017 to 2024). A primary or metastatic malignant neoplasm involving the esophagus. "The gene RP5–1024C24.1 lacks current research, while DCDC1 has been implicated in esophageal cancer." (PMID 39086896, 2024). "There has other research found that DCDC1 was significantly associated with esophageal carcinoma as a mutated gene." (PMID 32266149, 2020).
cataract (1 paper, 2021). Partial or complete opacity of the crystalline lens of one or both eyes that decreases visual acuity and eventually results in blindness. "We had 1 patient (patient 3-I) with a 3′ UTR gene deletion extending to involve ELP4 and DCDC1; she presented with partial iris hypoplasia, cataracts, glaucoma, and a retinal detachment in a surgically naive eye but no reported ARK." (PMID 34101622, 2021).
ocular coloboma (1 paper, 2018). "The 681 kb deletion downstream of the PAX6 gene including the DCDC5, DCDC1, DNAJC24, IMMP1L genes and a part of the ELP4 gene has been discovered in a patient with ocular coloboma." (PMID 29460221, 2018).
DCDC1 also shares sentences with these, for which no sentence is quoted: autism (2 papers); essential hypertension (2); Hypertension (2); WAGR syndrome (2); coronary atherosclerosis (1); glaucoma (1); Hypomagnesemia (1); Intellectual disability (1); optic nerve hypoplasia (1); Posterior polar cataract (1); tumor (1); type 2 diabetes (1).